BAG3 (BAG cochaperone 3)
Diseases named in the same sentence as BAG3 in open-access papers (continued):
Sharing a sentence is not in itself a finding about the gene and the disease.
atherosclerosis (2 papers, 2022 to 2025). A disease characterized by the build-up of fatty material and calcium deposition in the arterial wall resulting in partial or complete occlusion of the arterial lumen. "BAG3 is commonly associated with atherosclerosis, which is characterized by the abnormal accumulation of lipids (such as cholesterol and triglycerides) in the vascular wall." (PMID 41047495, 2025). "B cell lymphoma 2-associated athanogene (BAG3) was proven to participate in the regulation of tumor angiogenesis, neurodegenerative diseases, and cardiac diseases, but its role in atherosclerosis remains unclear." (PMID 35893075, 2022). "Our research illustrates that BAG3 has a protective effect against atherosclerosis and provides a new target for treating atherosclerosis." (PMID 35893075, 2022). "In summary, BAG3 mitigates atherosclerosis by suppressing EndMT via synthesizing a CASA complex with HSP70 and HSPB8 to activate autophagy." (PMID 35893075, 2022). "Here, we aim to investigate the role of BAG3 in atherosclerosis and elucidate the potential molecular mechanism." (PMID 35893075, 2022). "The current study aimed to investigate the role of BAG3 in the progress of atherosclerosis and the potential mechanisms." (PMID 35893075, 2022). "In addition, BAG3 overexpression reduced atherosclerotic lesions in ApoE−/− mice, indicating that BAG3 plays an important protective role in atherosclerosis." (PMID 35893075, 2022). "Taken together, BAG3 overexpression relieved the development of atherosclerosis." (PMID 35893075, 2022). "Our data suggested that overexpression of BAG3 could inhibit endothelial injury and rescue EndMT in vivo and in vitro, illustrating that BAG3 might be targeted therapeutically to restore atherosclerosis." (PMID 35893075, 2022). "The overexpression of BAG3 reduced plaque areas and improved atherosclerosis in ApoE−/− mice." (PMID 35893075, 2022). "Thus, we hypothesized that BAG3 might be a novel therapeutic target in the setting of atherosclerosis." (PMID 35893075, 2022). "However, the effect of BAG3 on atherosclerosis remains unclear." (PMID 35893075, 2022). "In this study, ApoE−/− mice were given a tail-vein injection of BAG3-overexpressing lentivirus and fed a 12-week high-fat diet (HFD) to investigate the role of BAG3 in atherosclerosis." (PMID 35893075, 2022). "To further understand the role of BAG3 on EndMT in the atherosclerosis model, we used BAG3 pcDNA with and without Apoptozole in ox-LDL treated HUVECs." (PMID 35893075, 2022).
brain injury (2 papers, 2017 to 2025). Acute and chronic (see also brain INJURIES, CHRONIC) injuries to the brain, including the cerebral hemispheres, CEREBELLUM, and brain STEM. "Following brain trauma SQSTM1−/− mice show decreased Bag3 mRNA expression levels 5 days after trauma." (PMID 29311767, 2017).
breast tumor (2 papers, 2017 to 2022). "We therefore next examined the co-expression correlation between HSPs and co-chaperones including HSP90 family (HSP90AA1, HSP90AB1), HSP70 family (HSPA1A, HSPA1B, HSPA8) and BAG family (BAG1, BAG2, BAG3) among 960 breast tumor samples registered in the Cancer Genome Atlas (TCGA)." (PMID 36114410, 2022). "CXCR4 mRNA level was positively correlated with BAG3 mRNA expression in breast tumor tissues." (PMID 28703799, 2017).
broken heart syndrome (2 papers, 2015 to 2023). "Of interest, genetic variants in BAG cochaperone 3 (BAG3), which has an important role in autophagy through binding to SQSTM1, have been associated with Takotsubo cardiomyopathy." (PMID 37569694, 2023).
childhood cancer (2 papers, 2025). "In addition, recent data from 6420 childhood cancer survivors showed that common variants of TTN and BAG3 were associated with a reduced risk of late-onset cardiomyopathy." (PMID 40868441, 2025).
cognitive deficits (2 papers, 2024 to 2025). "Specific overexpression of neuronal BAG3 in the hippocampus attenuated AD-like pathology and cognitive deficits induced by TBI in hTKI mice, which is associated with increased ALP-related proteins." (PMID 39394356, 2024). "In conclusion, we demonstrate that neuronal BAG3 attenuates tau hyper-phosphorylation and cognitive deficits induced by TBI probably via the increased ALP." (PMID 39394356, 2024). "Importantly, specific overexpression of BAG3 in neurons attenuated AD-like pathology and cognitive deficits induced by TBI probably via the up-regulation of autophagy-lysosome pathway (ALP)." (PMID 39394356, 2024). "Furthermore, while BAG3 has been extensively investigated in its relationship with tau pathology, we investigated the relationship of BAG3, tau pathology, and cognitive deficits in the context of TBI for the first time." (PMID 39394356, 2024). "Our data suggest that targeting neuronal BAG3 may be a therapeutic strategy for preventing or reducing AD-like pathology and cognitive deficits induced by TBI." (PMID 39394356, 2024). "Specific overexpression of BAG3 in neurons of hTKI mice attenuated the inhibition of ALP, ptau, synaptic dysfunction, and cognitive deficits induced by TBI." (PMID 39394356, 2024). "Our findings demonstrate a cell type-specific role of BAG3 in TBI-mediated ALP dysfunction, AD-like pathology, and cognitive deficits." (PMID 39394356, 2024). "Our findings suggest that targeting neuronal BAG3 and the ALP may be a therapeutic strategy for preventing or reducing tau pathology and cognitive deficits induced by TBI." (PMID 39394356, 2024). "Thus, it will be interesting to investigate the molecular state of microglia, astrocytes, and OLG at different time points after TBI, the neuron–glia communication, and the involvement of glial BAG3 in TBI-induced AD-like pathology and cognitive deficits in future." (PMID 39394356, 2024).
dementia (2 papers, 2023 to 2024). Loss of intellectual abilities interfering with an individual's social and occupational functions. "Notably, we have previously reported that BAG3 is significantly reduced in neurons of human AD compared to non-dementia controls." (PMID 39394356, 2024). "Within these genes, through proteomic study, BAG3 may affect AD by influencing the interpretation of Aβ and tau protein, and patients with AD have much lower levels of SEZ6 in their cerebrospinal fluid than those without dementia." (PMID 37867597, 2023).
desminopathies (2 papers, 2025). "Our data delineate a pathogenetic link between the myeloid leukaemia factors 1 and 2 and the myofibrillar myopathy– and protein quality control‐related proteins Dnajb6 and Bag3 in the context of desminopathies." (PMID 41165044, 2025). "Notably, Mlf2, an interaction partner of Mlf1, has been shown be enriched in protein aggregates in human desminopathies thus highlighting a novel and conceivable disease link between Mlf1 and Mlf2 related transcriptional control and Dnajb6 and Bag3 mediated protein quality control." (PMID 41165044, 2025).
distal hereditary motor neuropathy (2 papers, 2023 to 2025). "Similar to BAG3 and HSPB8, mutations in the genes coding for DNAJB2, HSPB1 and HSPB3 have been associated with distal hereditary motor neuropathy (dHMN), including Charcot–Marie–Tooth disease." (PMID 40757567, 2023).
endometrioid endometrial adenocarcinoma (2 papers, 2017 to 2024). "Moreover, the BAG3 protein was found to be specifically overexpressed in endometrioid endometrial adenocarcinomas, suggesting a function of BAG3 in the maintenance of cell survival in uterine cancer." (PMID 28680391, 2017).
fibrosis (2 papers, 2025). the formation of excess fibrous connective tissue in an organ or tissue in a reparative or reactive process. "Analysis of cell type–specific conditional knockout engineered heart tissues revealed an essential contribution of CF BAG3 to contractility and cardiac fibrosis, recapitulating the phenotype of DCM." (PMID 39744939, 2025).
gastric cancer (2 papers, 2024 to 2026). A primary or metastatic malignant neoplasm involving the stomach. "Notably, knockdown of CREB3L4 inhibited autophagy and alleviated cisplatin resistance in gastric cancer cells by down-regulating BAG3." (PMID 42098970, 2026). "Furthermore, BAG3 expression was inhibited following CREB3L4 knockdown in gastric cancer cells." (PMID 42098970, 2026). "However, whether the CREB3L4/BAG3 axis regulates autophagy and contributes to cisplatin resistance in gastric cancer cells remains unclear." (PMID 42098970, 2026).
myofibrillar myopathy 6 (2 papers, 2019 to 2026). Selcen type muscular dystrophy is characterized by progressive limb and axial muscle weakness associated with cardiomyopathy and severe respiratory insufficiency during adolescence. "There is also myofibrillar myopathy 6 (MFM6), a severe neuromuscular disorder caused by mutations in BCL2 associated athanogene 3 (BAG3), a gene encoding a factor that regulates the HSP70 protein family." (PMID 31097008, 2019).
myositis (2 papers, 2024 to 2025). "Recent proteomic and transcriptomic profiling of anti-Ku myositis identified marked activation of autophagy, proteasome, and hnRNP-linked stress pathways, together with sarcoplasmic aggregates containing p62, BAG3, myotilin and immunoproteasome β5i." (PMID 40599787, 2025).
non-small cell lung carcinoma (2 papers, 2024 to 2026). A group of at least three distinct histological types of lung cancer, including non-small cell squamous cell carcinoma, adenocarcinoma, and large cell carcinoma. "Recent report suggest that USP32 promotes tumor progression by activating the RAF/MEK/ERK signaling pathway and inducing epithelial-mesenchymal transition (EMT) by stabilizing BAG3 protein expression in non-small cell lung cancer." (PMID 41356798, 2026). "After that, USP32 and BAG3 were tested in non-small cell lung cancer cell lines in order to experimentally validate their protein levels." (PMID 39030175, 2024). "The findings demonstrated a favorable correlation between USP32 and BAG3 expression in a variety of non-small cell lung cancer cell lines." (PMID 39030175, 2024). "Overall, our work reveals USP32 as a potential therapeutic target for patients with non-small cell lung cancer and complements the deubiquitination regulatory network of BAG3." (PMID 39030175, 2024).
pancreatitis (2 papers, 2015 to 2025). Inflammation of the pancreas. "The already vulnerable myocardium from BAG3-associated DCM, aggravated by a potential viral trigger and acute systemic inflammation from pancreatitis, could have caused this presentation." (PMID 41250780, 2025).
polyneuropathy (2 papers, 2014 to 2015). A disease or disorder affecting more than one nerve. "Interestingly, we detected a polyneuropathy in more than a quarter of the MFM patients, including a BAG3 and a MYOT case." (PMID 25208129, 2014).
Spinocerebellar ataxia type 3 (2 papers, 2017 to 2025). "Remarkably, post-mortem analyses of brain tissue from patients with Alzheimer disease, Parkinson disease, Huntington disease, and spinocerebellar ataxia type 3 (SCA3) have revealed increased HSPB8 and BAG3 expression in astrocytes within affected cerebral areas." (PMID 40385290, 2025).
Ureteral obstruction (2 papers, 2022 to 2024). Obstruction of the flow of urine through the ureter. "Similarly, C. sinensis could mitigate the fibrosis by inhibiting the expression of Bcl-2-associated athanogene 3 (BAG3) and α-SMA in unilateral ureteral obstruction (UUO) rats, and regulating the formation of EMT." (PMID 35645822, 2022). "Using a rat model of unilateral ureteral obstruction (UUO), researchers observed that Cordyceps sinensis can inhibit BAG3 expression, thus reducing renal fibrosis." (PMID 38645562, 2024).
acute kidney injury (1 paper, 2025). Sudden and sustained deterioration of the kidney function characterized by decreased glomerular filtration rate, increased serum creatinine or oliguria. "Bcl-2-associated athanogene 3 (BAG3) also plays a protective role in sepsis-induced acute kidney injury (AKI), and studies have shown that sevelamer sodium can attenuate AKI in a rat sepsis model through inhibition of the PI3K/Akt pathway, with BAG3 involved in this protective mechanism." (PMID 40823184, 2025).
autosomal dominant dilated cardiomyopathy (1 paper, 2021). Dilated cardiomyopathy, characterized by dilation and contractile dysfunction of the left and right ventricles, with an autosomal dominant pattern of inheritance. "Bag3, for example, is associated with autosomal dominant dilated cardiomyopathy with partial penetrance and has been described as haploinsufficient." (PMID 34504093, 2021).
Cerebral ischemia (1 paper, 2020). Restriction of arterial blood supply to the brain associated with insufficient oxygenation to support the metabolic requirements of the tissue. "Depending on the BAG1/BAG3 ratio and expression level of HDAC6, a switch from the ubiquitin-proteasome pathway to the autophagy-lysosome pathway occurs between 10 and 30 min during cerebral ischemia." (PMID 32089771, 2020).
cervical intraepithelial neoplasia (1 paper, 2024). "Bcl-2-associated athanogene 3 (BAG3), a protein involved in the stress response, is a promising biomarker for cervical intraepithelial neoplasia." (PMID 38279253, 2024).
Cirrhosis (1 paper, 2025). A chronic disorder of the liver in which liver tissue becomes scarred and is partially replaced by regenerative nodules and fibrotic tissue resulting in loss of liver function. "Indeed, notably, serum BAG3 levels were more than two-fold higher in the cirrhosis/HCC subgroup (143.8 ± 245.1 pg/mL) than in the uncomplicated MASLD group (61.8 ± 220.9 pg/mL; p = 0.011), indicating a potential link between BAG3 concentrations in the sera and disease severity." (PMID 41373448, 2025).
coronary artery disease (1 paper, 2022). "BAG3 is significantly and negatively associated with systolic and diastolic blood pressure, whereas MIF and APOA5 are associated with coronary artery disease." (PMID 35964012, 2022). "Multivariable MR showed that association of BAG3, MIF and APOA5 with HF were mediated by the blood pressure and coronary artery disease." (PMID 35964012, 2022). "However, some proteins such as BAG3, MIF and APOA5 show concordant associations between HF, the blood pressure (BAG3) and coronary artery disease (MIF and APOA5)." (PMID 35964012, 2022).
cystic fibrosis (1 paper, 2022). Autosomal recessive disorder caused by pathogenic variants in the CFTR gene (cystic fibrosis transmembrane conductance regulator), which encodes a chloride and bicarbonate channel expressed in epithelial cells, and follow the diagnosis criteria. "In support to this notion in bronchial epithelial cells of cystic fibrosis patients, inhibition of BAG3 was shown to rescue defective autophagy." (PMID 35834635, 2022).
depression (1 paper, 2024). "Cinnamaldehyde has been reported to have many beneficial health-promoting effects, including anti-bacterial, anti-cancer, anti-inflammation, anti-depression, and anti-aging effects, as well as providing neurocardiac protection, possibly through BAG3 upregulation." (PMID 39684673, 2024).
dilatation (1 paper, 2025). "Dynamic BAG3-/- CMs decreased cell area and increased cell aspect ratio compared to static BAG3-/- CMs, indicating an eccentric cell thinning phenotype commonly observed in myocardial dilatation." (PMID 41328308, 2025).
Diplopia (1 paper, 2014). Diplopia is a condition in which a single object is perceived as two images, it is also known as double vision. "Only one other adult-onset patient with BAG3-related MFM has thus far been described: a woman harbouring the p.261-265 RAASP deletion in BAG3, who showed involvement of the orbicularis oculi muscles and the lower limb muscles, as well as photophobia and diplopia, starting at the age of 60 years." (PMID 25208129, 2014).
head and neck squamous cell carcinoma (1 paper, 2025). A squamous cell carcinoma that arises from any of the following anatomic sites: lip and oral cavity, nasal cavity, paranasal sinuses, pharynx, larynx, and salivary glands. "Given the similarities in tumor–stroma interactions, BAG3 may play a comparable role in head and neck squamous cell carcinoma (HNSCC)." (PMID 40507324, 2025). "Our findings indicate that immunohistochemical testing for BAG3 positivity could aid in diagnosing tumor progression and prognosis in head and neck squamous cell carcinoma (HNSCC), with potential implications for therapeutic strategies." (PMID 40507324, 2025).
hemorrhagic fever (1 paper, 2018). An infectious disease caused by certain viruses or bacteria that can damage the walls of tiny blood vessels, making them leak, and can hamper the blood's ability to clot and cause severe, life-threatening illness. "BAG3 has now been shown to negatively regulate egress of VLPs from three different hemorrhagic fever viruses, and thus a better understanding of its role in regulating egress of perhaps an even wider array of viral pathogens is warranted." (PMID 30011814, 2018). "Our results suggest that CASA and specifically BAG3 may represent a novel host defense mechanism, whereby BAG3 may dampen egress of several hemorrhagic fever viruses by interacting and interfering with the budding function of viral PPxY-containing matrix proteins." (PMID 30011814, 2018).
Hepatic fibrosis (1 paper, 2025). The presence of excessive fibrous connective tissue in the liver. "In this study, we demonstrate for the first time that serum BAG3 concentrations are positively associated with hepatic fibrosis severity in patients with MASLD." (PMID 41373448, 2025). "This study investigated the role of the stress-response co-chaperone BAG3 as a circulating biomarker of hepatic fibrosis and its association with PNPLA3 and TM6SF2 genotypes." (PMID 41373448, 2025). "This study identifies BAG3 as potentially informative biomarker of hepatic fibrosis in patients with MASLD." (PMID 41373448, 2025). "We observed a significant positive correlation between serum BAG3 and FIB-4 scores (Spearman’s ρ = 0.158, p = 0.012), suggesting that higher BAG3 concentrations are associated with advanced liver fibrosis." (PMID 41373448, 2025). "Further longitudinal and mechanistic studies are needed to validate BAG3 as a prognostic biomarker and to clarify whether it might represent a therapeutic target in liver fibrosis." (PMID 41373448, 2025). "In this study, we explore the significance of BAG3 detection in patients’ sera in hepatic fibrosis within the context of MASLD and its interaction with key genetic variants PNPLA3 and TM6SF2, aiming to unravel potential new insights into the molecular mechanisms driving disease progression." (PMID 41373448, 2025). "In a well-characterized Southern European cohort of 146 MASLD patients, liver fibrosis was assessed using the FIB-4 index, serum BAG3 levels were quantified by ELISA, and genotyping for PNPLA3 and TM6SF2 variants was performed." (PMID 41373448, 2025). "Although the role of BAG3 in hepatic physiology is less well characterized, emerging evidence suggests that it may influence hepatocyte survival, autophagic flux, and hepatic stellate cell (HSC) activation—all critical processes in liver fibrosis development." (PMID 41373448, 2025).
HIV-1 infection (1 paper, 2012). The type species of lentivirus and the etiologic agent of acquired immunodeficiency syndrome (AIDS). "In addition, recent studies have demonstrated that down regulation of Bag3 sensitizes primary microglial cells to caspase-3 activation following HIV-1 infection, suggesting a unique role for Bag3 in the interaction of HIV-1 with host cells." (PMID 22984599, 2012).